NRP1 (neuropilin 1)
Diseases named in the same sentence as NRP1 in open-access papers (continued):
Sharing a sentence is not in itself a finding about the gene and the disease.
tumor (continued). "Finally, NRP1 transcripts are targeted by several microRNAs (miR), such as miR-9, miR-181b, miR-320 and miR-338, with the effect of modulating tumor angiogenesis, invasion and metastasis in experimental models." (PMID 31027288, 2019). "NRP1 was identified as a novel Cltx target which enhances tumor drug uptake." (PMID 31208428, 2019). "NRP-1 depletion significantly inhibited cell proliferation in situ and reduced tumor vasculature." (PMID 31572065, 2019). "Targeting the b1/b2 tandem domain of NRP1 with a monoclonal antibody results in a reduced density of the vascular network lacking associated pericytes, and delays tumor growth only in combination with anti-VEGF therapy, but is ineffective when used alone." (PMID 30717262, 2019). "As human CD8+ TIL expressed substantial amounts of Nrp-1, this raises the question as to whether its interaction with Sema-3A contributes to the T-cell dysfunction often observed in the tumour microenvironment." (PMID 31350404, 2019). "Therefore, we further verified the effect of NRP1 on the secretion of these inflammatory factors at mRNA and protein levels in a tumor-bearing mouse model." (PMID 31417646, 2019). "However, studies showed that adding external VEGF did not have an impact on the apoptosis of cancer cells when NRP-1 was knocked down, which proved the crucial role of NRP-1 in the anti-tumor effect of VEGF/NRP-1." (PMID 30978940, 2019). "Then, the fragment binds to neuropilin-1 and penetrates the tumor parenchyma more deeply." (PMID 31346334, 2019). "Notably, when using the i.p. route of injection, anti-PD-1 plus anti-Nrp-1 combination had similar effects on tumour progression than anti-PD-1 plus anti-CTLA-4." (PMID 31350404, 2019). "However, in murine models deprived of NRP1+ monocytes, tumor growth and metastatic progression were actually inhibited." (PMID 30658382, 2019). "Such transcellular interactions occur between EC-anchored VEGFR2 and NRP1 of tumor cells." (PMID 30717262, 2019). "After subsequent proteolytical unmasking of the CendR motif by the tumor-related urokinase plasminogen activator (uPA) and binding to NRP1, the peptides are micropinocytotically taken up and, subsequently, by a transcytosis cascade, distributed deep into the tumor parenchyma." (PMID 30717262, 2019). "Interestingly, it has been reported that the high-level expression of NRP1 in tumor cells and the upregulation of PlGF in the cerebellar stroma are required for the growth and spread of medulloblastoma in mice." (PMID 31216652, 2019). "We also show here that anti-Nrp-1 neutralising mAb, in particular when associated with anti-PD-1, re-established ex vivo the functionality of these T cells, such as increase of perforin expression and TCR-mediated cytotoxicity toward the cognate tumour." (PMID 31350404, 2019). "Furthermore, some targets (αvβ3 integrin, nucleolin, NRP-1, ED-A and TF) also overexpress on certain types of tumor cells." (PMID 33568892, 2019). "Moreover, CD8+ TIL from mice treated i.p. with anti-Nrp-1 plus anti-PD-1 expressed higher levels of granzyme B and mediated stronger cytotoxic activity toward autologous MC-38 tumour cells than TIL from mice treated with each mAb alone." (PMID 31350404, 2019). "Antitumor activity of ER-472 in xenografts correlated to tumor NRP1 expression." (PMID 31208428, 2019). "Also, in biliary tract cancer with strong expression of NRP1 and NRP2, Wnt and PI3K signaling are associated with tumor angiogenesis." (PMID 30717262, 2019). "Consequently, these advantages facilitate the transfer of CRGDK fragments from integrins to neuropilin-1 and consequently deeper penetration into the tumor." (PMID 31346334, 2019). "This bulk transport pathway has implications in extravasation, drug delivery and penetration of tissue barriers, and because tumor cells overexpress NRP1, it may be particularly applicable for delivery of drugs into tumors, as demonstrated with ER-472." (PMID 31208428, 2019).
tumor (continued). "Induction of tumor-specific permeability of blood vessel walls via the NRP1-MET signaling axis may allow to use such agents at lower systemic dosage and therefore with better tolerance and less side effects." (PMID 29854288, 2018). "Migration of HT1080 cells along a rhodocetin-αβ gradient was concentration-dependent and could be inhibited by blocking MET, suggesting that rhodocetin-αβ induced tumor cell motility along the NRP1-MET signaling axis, similar as in ECs." (PMID 29854288, 2018). "NRP1 expression was present in both endothelial cells and surrounding tumor cells." (PMID 30027561, 2018). "Using proximity ligation assay, VEGFR2/NRP1 trans‐complexes were identified in human PDAC tumor tissue, and its presence was associated with reduced tumor vessel branching, reduced tumor cell proliferation, and improved patient survival after adjusting for other known survival predictors." (PMID 30027561, 2018). "Due to the specific neuropilin-1/MET co-distribution on cells lining such abnormal tumor vessels in contrast to normal endothelial cells, rhodocetin-αβ formed the necessary trimeric signaling complex of rhodocetin-αβ-MET-neuropilin-1 only in these abnormal tumor vessels." (PMID 29854288, 2018). "Importantly, tumor cell proliferation was significantly reduced in the presence of VEGFR2/NRP1 trans‐complexes." (PMID 30027561, 2018). "We cannot exclude that tumor cell‐expressed NRP1 may influence tumor angiogenesis through other interactions in addition to that with VEGFR2." (PMID 30027561, 2018). "While transcript and protein levels may not strictly correlate 32, we found similar trends in the different analyses, namely that GAC and PDAC both expressed NRP1 transcript and protein in tumor cells, albeit at higher levels in PDAC." (PMID 30027561, 2018). "When expressed by tumor cells, neuropilin-1 seems to increase VEGF-mediated angiogenesis." (PMID 29915721, 2018). "Importantly, the expression of neuropilin-1 or its homologue neuropilin-2 by cancer cells was related to tumor initiation, growth, metastasis and immunity." (PMID 29547633, 2018). "We have identified an intriguing change in the DNA methylation status of the CNS2 locus of Foxp3 in the Nrp1-deficient Tregs from the tumor microenvironment but no loss in Foxp3 expression." (PMID 30400822, 2018). "Studies showed that the specific inhibitor of Nrp1 named EG00229 reduced tumor growth." (PMID 30123112, 2018). "Altogether, these results suggest that the tumor-promoting effects of HS3ST3B could be related to the role of Nrp1 in the formation of signaling complexes with growth factors and their cognate receptors." (PMID 30360368, 2018). "Moreover, in HT1080 cells NRP1 is upregulated under hypoxia, along with other angiogenic markers in a mouse xenograft tumor model, in which HT1080 cells form functional vasculogenic mimicry vessels." (PMID 29854288, 2018). "In the majority of tumor types, vascular NRP1 expression was seen in less than 50% of the samples." (PMID 30027561, 2018). "The binding of the CendR peptide to NRP-1 activates a macropinocytosis-related transport pathway that is regulated by nutrient availability mediates a transcytosis cascade and results in the distribution of the payloads deep into the tumor parenchyma." (PMID 29772690, 2018). "However, the exact mechanisms of NRP‐1‐mediated tumor angiogenesis are difficult to pinpoint because NRP‐1 interacts with numerous cancer‐promoting ligands and receptors." (PMID 30216699, 2018). "Moreover, targeting placental growth factor (PlGF)/NRP1 with monoclonal antibodies induced a direct antitumor effect in MB, resulting in tumor regression, decrease of metastasis and increase of survival in mouse models." (PMID 29632646, 2018). "After leaking from tumor blood vessels, rhodocetin-αβ might also interact with NRP1 on surrounding pericytes and thereby further destabilize the tumor vasculature." (PMID 29854288, 2018).
tumor (continued). "CendR motif binds to NRP-1 protein, which is overexpressed in tumor cells and tumor vasculature." (PMID 29721153, 2018). "Moreover, a tumor-homing peptide with a C-end rule sequence, tLyP-1, is able to promote tissue penetration via the neuropilin-1-dependent internalization pathway, enhancing the targeting efficiency and tumor penetration." (PMID 30340364, 2018). "Neuropilin-1 is an angiogenic receptor that can be expressed both by endothelial and tumor cells." (PMID 29915721, 2018). "Rhodocetin-αβ can trigger NRP1-MET signaling in tumor cells, TECs, and endothelial cells alike." (PMID 29854288, 2018). "Our lab has previously shown that GAM-specific ablation of NRP1, or global pharmacological inhibition of this co-receptor, slows tumor progression in a mouse model of GB, in a similar fashion, by inhibiting neoangiogenesis and reducing immunosuppressive signaling." (PMID 30479695, 2018). "Altogether, our findings support the idea that the tumor-promoting effects of HS3ST3B could be dependent on the expression of Nrp1 in cancer cells." (PMID 30360368, 2018). "Previously published data suggested that other Class III semaphorin members, Sema3B and Sema3F, could act as tumor suppressors as they bind antagonistically to NRP-1 and NRP-2, and inhibit angiogenesis." (PMID 30598022, 2018). "We report several genes that have not previously been associated with NRP-1 overexpression, which include oncogenes, tumor suppressors and genes involved in cancer-related pathways and protein binding function." (PMID 29728077, 2018). "Indeed, mice with GAM specific deletion of NRP1 resulted in slower tumor growth, reduced tumor vascularity and increased survival." (PMID 29067024, 2017). "Importantly, concurrent inhibition of KRASmt and NRP1 in the tumor cells reverses the increased viability and leads to tumor inhibition." (PMID 29018205, 2017). "Hence, the reactivation of the Nrp1-TGFβ pathway in GBM cells to promote tumor progression is a likely pathological recapitulation of events involved in brain vascular development." (PMID 28938007, 2017). "Confirmed insight into the function and prognostic value of NRP1 expression on tumor-associated DCs is still lacking, including the regulation of NRP1 expression by TIDCs." (PMID 29067024, 2017). "Additionally, TNBC cases (n = 14) had significantly increased NRP-1 expression in tumor tissue compared to the luminal B (n = 16, p = 0.043) and B-like (n = 14, p = 0.005) subtypes and higher PlGF expression compared to luminal B cases (n = 16, p = 0.026)." (PMID 28607365, 2017). "MiR-320 was identified as a tumor suppressor transcript in OSCC, and it was stated that it might play a crucial part in repressing tumor angiogenesis by silencing Nrp1 expression." (PMID 29206174, 2017). "In contrast to the silent expression of healthy donor peripheral Tregs, Neuropilin-1 is expressed by approximately 90% of tumor infiltrating Tregs in cancer patients and increased percentage of human Neuropilin-1+ intratumoral Tregs correlates with poor prognosis." (PMID 29225597, 2017). "A starting point may be the HTICS Cell migration pathway genes (Nrp1, Npy, Cldn8) and their substitutes (Klrd1, Spink5, Itga8) identified herein—but other known markers of cancer cell dissemination or circulating tumor cells may be equally informative." (PMID 28632792, 2017). "Indeed, in endothelial cells and tumor cells Nrp1 can promote the internalization of the VEGFR2 cell surface protein." (PMID 28938007, 2017). "This indicates a tumor promoting role for NRP1 in Tregs and poor clinical outcome." (PMID 29067024, 2017). "The knockdown of both KRAS and NRP1 in PANC-1 cell lines (KRASmt) inhibited tumor formation." (PMID 29018205, 2017).
tumor (continued). "We assessed the contribution of cytokine stimuli to induce surface B7x expression on cancer cells and the role of tumor-expressed B7x in a murine pulmonary metastasis model, and finally evaluated the potential interaction between B7x and Neuropilin-1, a suggested potential cognate receptor." (PMID 29137299, 2017). "Collectively, these experiments show that delivery of siRNA therapeutics guided by the affinity interactions between the tumor-homing peptide iRGD and cell-surface αv integrins and neuropilin-1 resulted in potent suppression of TNFα secretion in a receptor-specific fashion." (PMID 29018206, 2017). "In addition to analyzing Nrp1 regulation of tumor growth in the LN229 GBM cell line, we also analyzed primary stem-like GBM cells (GSCs) derived from patient tumors." (PMID 28938007, 2017). "Nrp1 protein levels were elevated in five of the six tumor lysates analyzed." (PMID 28938007, 2017). "Furthermore, a review of relevant published reports detailing the effects of NRP1 in various tumors supports the premise that down regulation of NRP1 promotes tumorigenesis in the presence of KRASmt and suppresses tumor formation with KRASwt." (PMID 29018205, 2017). "NRP1 downregulation in the PDAC cell line PANC-1 and NSCLC cell line A549 (KRASmt) resulted in increased tumor growth, whereas NRP1-deficient PDAC BxPC-3 cells and NSCLC H226 cells (KRASwt) exhibited decreased tumor growth as compared to that of parental cells." (PMID 29018205, 2017). "Similarly, NRP1 can associate with GIPC1 and promote tumor progression through the KRAS/ERK signaling pathway." (PMID 29018205, 2017). "Treg-specific deletion of Nrp1 was found to block tumor growth in several animal models of cancer." (PMID 29463952, 2017). "qPCR analysis of FACS-isolated tumor cells confirmed the Nrp1 expression pattern." (PMID 28887477, 2017). "We hypothesized that both VS-derived primary cell cultures and archived tumor specimens from patients with unilateral, sporadic VS overexpressed sufficient amounts of αv integrin and NRP-1." (PMID 29018206, 2017). "Since KRAS mutation is among the most common oncogenic mutations associated with tumor growth, we hypothesized that KRAS mutation status may influence the role of NRP1 in tumorigenesis." (PMID 29018205, 2017). "In sum, these results suggest that both primary human VS cultures and an NF2-derived VS cell line overexpress αv integrins and NRP-1 on the cell surface, which can be harnessed for receptor-targeted, tumor-penetrating delivery of therapeutics via the CendR pathway." (PMID 29018206, 2017). "We demonstrated that a synthetic transmembrane peptide mimicking the TMD of PlexA1 (MTP-PlexA1) reduced GBM cell proliferation and blocked VEGF-induced tumor cell dissemination due to disruption of NRP1/PlexA1 heterodimerisation and subsequent inhibition of the PlexA1 dependent Rho-GTPase." (PMID 27506939, 2016). "Furthermore, PDAC is characterized by aberrant expression of NRP-1, often correlated with tumor progression and poor patient prognosis." (PMID 27542226, 2016). "Next, we assessed tumor-derived Nrp-1-specific Foxp3+ Treg cell phenotypes during tumorigenesis." (PMID 27075020, 2016). "The killing activity of TU17:MTD or TU17-2:MTD on tumor tissues was substantially inhibited when the anti-NRP-1 antibody was pre-injected into tumor-bearing mice in vivo, and the extent to which TU17:MTD or TU17-2:MTD injection reduced tumor volume at day 1 was significantly decreased." (PMID 27083053, 2016). "NRP1 can indeed synergize with these extracellular matrix receptors to promote cancer cell proliferation, migration or colony formation in soft agar in vitro and to stimulate in vivo tumor growth and vascularization." (PMID 27798666, 2016). "Interestingly, recent evidences have implicated a novel regulatory role of NRP-1 in epithelial-to-mesenchymal transition (EMT); an evolutionary conserved developmental process, which is evoked during tumor invasion and metastasis of several cancers." (PMID 27542226, 2016).
tumor (continued). "Moreover, the group of Perret and colleagues described that a heptapeptide also inhibiting VEGF binding to NRP1 reduced tumor volume, blood vessel density in orthotopic mammary MDA-MB-231 tumors." (PMID 27351129, 2016). "Besides, recent studies suggested that NRP1 also affects tumor microenvironment by facilitating integrin functions in fibroblasts." (PMID 27863391, 2016). "When performing a proximity ligation assay on tumor tissue sections we could visualize a two-fold reduction of interactions of PlexA1 and NRP1 when mice had been treated with MTP-PlexA1 (−48.5%, p = 0.0051, Mann Whitney test)." (PMID 27506939, 2016). "Furthermore, blockade of Nrp-1 resulted in significantly augmented tumor-derived CD4+IL-17A+ (Th17) cells." (PMID 27075020, 2016). "Most studies seeking to target NRP1 function have assessed a candidate agent's ability to modulate endothelial cell phenotypes in commonly used in vitro assays and/or examined their ability to inhibit tumour growth and angiogenesis in mouse models." (PMID 26923176, 2016). "However, the facts that the penetration and killing activity of TU17:MTD on tumor cells can be blocked by anti-NRP-1 antibody indicate that TU17:MTD targets or possibly binds to NRP-1." (PMID 27083053, 2016). "NRP-1 is also expressed in a variety of cancers, suggesting a critical role in tumor progression." (PMID 27047798, 2016). "TU17:MTD penetrated into tumor cells by targeting to Neuropilin-1, which could be blocked by anti-NRP-1 antibody." (PMID 27083053, 2016). "Furthermore, Nrp-1 acts as a key mediator of Foxp3+ Treg cell infiltration into the tumor site, resulting in a dampened anti-tumor immune response." (PMID 27075020, 2016). "In support of our results, blockage of NRP-1 inhibited tumor growth and VEGF-mediated angiogenesis." (PMID 26795388, 2016). "Firstly we inoculated tumor cells subcutaneously into the flank of nude mice to test whether NDGA administration affects NRP1 expression in vivo." (PMID 27863391, 2016). "Moreover, Treg-mediated immunosuppression can be limited by reducing tumor-derived Treg Nrp-1 levels." (PMID 27075020, 2016). "Conversely, Nrp-1-positive tumor-derived Treg cells were decreased." (PMID 27075020, 2016). "We believe that therapies directed at targets like NRP-1 to inhibit EndMT have tremendous translational implications as they could delay PDAC tumor progression, possibly owing to impaired angiogenesis as well as limited CAF recruitment." (PMID 27542226, 2016). "In addition to its prominent role in endothelial cells, NRP1 is also expressed in cell types as diverse as neurons, immune cells, and tumor cells." (PMID 26051942, 2015). "Several strategies have been explored to counteract the tumor promoting effects of NRP-1 function, employing different tools: recombinant sNRP-1, class 3 semaphorins, monoclonal antibodies (mAbs), peptides and peptidomimetics, small interfering RNAs (siRNAs) or microRNAs." (PMID 26090340, 2015). "This sensitisation to NRP1 perturbations that occurs upon suppressing β3-integrin means that we can target both molecules simultaneously to significantly improve inhibition of growth and angiogenesis in both new and established tumours." (PMID 26159543, 2015). "The distribution of FAM-tLyP-1 in the tumor tissue was consistent with expression of NRP1." (PMID 26398657, 2015). "The distribution of FAM-tLyP-1 was consistent with NRP1 expression in the same tumor section." (PMID 26398657, 2015). "NRP-1 is expressed in pDCs and in a subset of Tregs and favors the transendothelial migration of these cells in response to angiogenic factors produced by the tumor." (PMID 26090340, 2015). "Finally, expression of Nrp-1 on Tregs was required to limit anti-tumor immune responses and to cure established inflammatory colitis, whereas Nrp-1-induced transcriptome promoted Tregs stability and prevented these cells from further differentiation." (PMID 26495986, 2015).